DDX11 (DEAD/H-box helicase 11)
Diseases named in the same sentence as DDX11 in open-access papers (continued):
Sharing a sentence is not in itself a finding about the gene and the disease.
cancer (20 papers, 2018 to 2025). A tumor composed of atypical neoplastic, often pleomorphic cells that invade other tissues. "DDX11 has been associated with the development of various cancers, including lung and melanoma cancer." (PMID 39470258, 2024). "DDX11 has also been implicated in human cancer where it has been proposed to have an oncogenic role and possibly to constitute a therapeutic target." (PMID 38478595, 2024). "DDX11 encodes an iron–sulfur cluster DNA helicase required for development, mutation and over-expression in cancers." (PMID 39767827, 2024). "DDX11 encodes an iron–sulfur cluster DNA helicase required for development, mutated, and overexpressed in cancers." (PMID 33879618, 2021). "Here, we show that loss of DDX11 causes replication stress and sensitizes cancer cells to DNA damaging agents, including poly ADP ribose polymerase (PARP) inhibitors and platinum drugs." (PMID 33879618, 2021). "We uncover DDX11 as a potential target in tumors, including BRCA1/2-mutated cancers that acquired chemotherapeutic resistance, and pinpoint DDX11 mutations/loss as a useful biomarker of responsiveness to platinum drugs, PARP inhibitors, and ATRi." (PMID 33879618, 2021). "Previously, we showed that aggressive ccRCC, such as that associated with synchronous metastasis, recurrence, and/or cancer-specific death, is also associated with the upregulated expression of DDX11 mRNA in both plasma and frozen tissues." (PMID 33823929, 2021). "The E2F1/DDX11/EZH2 represents a promising therapeutic target in the clinical management of HCC that is one of the leading causes of cancer-related death globally." (PMID 33614480, 2020). "Searches through online catalogues of mutations in cancer reveal that the DDX11 gene is mutated, highly up-regulated and targeted for copy number amplification in many diverse tumour tissues." (PMID 30469382, 2018). "Thus, DDX11 loss sensitizes both HR-deficient and HR-proficient cancer cells to agents that necessitate repair via HR." (PMID 33879618, 2021). "We propose that DDX11 provides a mechanism of replication stress tolerance, which sustains survival of cancers, including BRCA1- and BRCA2-deficient cells, and can be exploited therapeutically through the development of specific inhibitors of DDX11 helicase activity." (PMID 33879618, 2021). "DDX11, a DNA helicase, has been implicated in rare genetic disease and human cancers." (PMID 33614480, 2020). "CHLR1/DDX11 depletion was also found to sensitize cancer cells to poly ADP-ribose polymerase (PARP) inhibitors and platinum-based chemotherapy and enhances the sensitivity to chemotherapy of cells with BRCA1 or BRCA2 mutations." (PMID 40136691, 2025). "This essentiality is supported by data from the DepMap project (a large-scale project aiming to systematically identify genetic and pharmacologic dependencies in a large panel of cancer lines), in which DDX11 is defined as a “common essential” gene." (PMID 38478595, 2024). "The yeast DDX11 homolog, CHL1, is a highly connected SL hub with many genes involved in cancer-relevant processes, but the mammalian GIs of DDX11 are only recently being defined." (PMID 38478595, 2024). "We confirm synthetic lethal relationships between DDX11 and the tumor suppressor cohesin subunit STAG2, which is frequently mutated in several cancer types and the kinase HASPIN." (PMID 38478595, 2024). "First, the upregulation of DDX11 across cancer types reached a median fold of 240%, which was higher than that of 97.4% of genes." (PMID 36474250, 2022). "For one particularly strong case, DDX11, we corroborated its essentiality in cancer cells via knockdown assays and revealed its fast evolution shaped by natural selection." (PMID 36474250, 2022). "Second, functional genomic data showed that the promoters of DDX11 and Timeless were constantly bound by E2F across all eight samples covering three cancer cell lines, while only 3.5% of genes showed the same pattern." (PMID 36474250, 2022).
cancer (continued). "Our findings revealed the important role played by DDX11 in preventing chromosomal segregation and apoptosis in advanced ccRCC cells, thereby maintaining the aggressiveness of this cancer." (PMID 34073906, 2021). "Altogether, our results define a DDX11-mediated DNA repair pathway that creates pharmaceutically targetable vulnerabilities in cancers." (PMID 33879618, 2021). "DDX11 loss greatly sensitizes both BRCA1- and BRCA2-deficient cancer cells to chemotherapeutic drugs, generating more DNA damage and genomic instability." (PMID 33879618, 2021). "The frozen tissue mRNA expression of DDX11 was identified as a biomarker for visceral adiposity and cancer aggressiveness." (PMID 33823929, 2021). "To comprehensively understand these four lncRNAs (LINC01224, CASC9, LINC00346, and TRPM2-AS) and seven target mRNAs (CCNF, PKMYT1, GCH1, TK1, PSAT1, ADAM33, and DDX11), we performed genome instability, immune, cancer stemness, and drug sensitivity analysis." (PMID 34368141, 2021). "As a result, targeting DDX11 confers improved chemotherapy responsiveness in both chemotherapy-sensitive and drug-resistant BRCA1/2-mutated cancers that regained homologous recombination proficiency by suppressor mutation or somatic reversion." (PMID 33879618, 2021). "Altogether, the results indicate that DDX11 targeting is useful in several cancers by increasing their sensitization to replication stress-induced chemotherapy." (PMID 33879618, 2021). "To investigate DDX11 functions in chemotherapy sensitization of cancer cells, we performed synthetic lethality drug screens in HeLa control (Ctrl) and DDX11 KO cells using 64 US Food and Drug Administration–approved drugs affecting different pathways." (PMID 33879618, 2021). "The results pinpoint DDX11 as a critical replication stress mitigating factor whose targeting can improve chemotherapeutic response in a range of cancers." (PMID 33879618, 2021). "Here, we find that targeting DDX11 sensitizes ovarian and other cancer cell lines to drug therapies involving cisplatin and the PARP inhibitor olaparib." (PMID 33879618, 2021). "As a result, DDX11 down-regulation aggravates the chemotherapeutic sensitivity of BRCA1/2-mutated cancers and resensitizes chemotherapy drug–resistant BRCA1/2-mutated cancer cells that regained homologous recombination proficiency." (PMID 33879618, 2021). "We propose DDX11 as a potential target in cancers by creating pharmacologically exploitable DNA repair vulnerabilities." (PMID 33879618, 2021). "We found that the expression of E2F1, a member of E2F protein family, was positively correlated with DDX11 mRNA expression in most cancer types." (PMID 32332880, 2020). "For RFS, those with cancer recurrence presented higher expression patterns of DDX11 and lower expressions of TMEM38B and PRUNE2, in both the univariate and multivariate analyses." (PMID 31963294, 2020). "Our findings provide the first evidence that DDX11 is overexpressed in ADC and has a close correlation with cancer progression, and the performance of DDX11 in predicting a poor prognosis in ADC is also satisfactory." (PMID 31413739, 2019). "DEAD/DEAH box helicase 11 (DDX11) was previously shown to be dysregulated and to exert oncogenic activity in cancer." (PMID 31413739, 2019). "DDX11 plays an important role in DNA replication, repair, and sister chromatid cohesion, and the yeast ortholog, Chl1, is a highly connected SL hub that interacts with many genes involved in cancer-relevant processes." (PMID 38478595, 2024). "Despite the critical roles of DDX11 in DNA replication and the development of cancer, its role in host defense is unknown." (PMID 39470258, 2024). "We thus predicted that the interaction between DDX11 and E2F or Timeless could be generalized across cancers and found two consistent patterns." (PMID 36474250, 2022). "We subsequently focused on DDX11, which promotes tumors across all cancer types." (PMID 36474250, 2022).
cancer (continued). "The molecular mechanism of DDX11 in DNA damage resistance of cancer cell lines is unclear." (PMID 33879618, 2021). "Here, we find that targeting DDX11, a gene whose up-regulation in several cancers correlates with poor patient prognosis (9, –11), sensitizes ovarian, uterine, and other cancers to PARP inhibitors and platinum chemotherapies by causing an accumulation of DNA damage and mitotic instability." (PMID 33879618, 2021). "The pathogenesis of how DDX11 is involved in adipogenesis and cancer progression is undetermined although some suggestions for the plausible mechanisms might be possible." (PMID 33823929, 2021). "We are under in vitro experiments on how DDX11 affects both adipogenesis and cancer progression." (PMID 33823929, 2021). "Furthermore, DDX11 was identified as one of the determinants for the sensitivity of cancer cells to PARP inhibitors." (PMID 33614480, 2020). "DDX11 has been reported to share sequence similarity to the Fe-S cluster-containing DNA helicases FANCJ and RTEL1 that are vital in genome stability maintenance and its function was implicated in rare genetic syndromes and cancer development." (PMID 32332880, 2020). "Recent studies have shown an oncogenic function for DDX11 in a few cancers." (PMID 31413739, 2019). "Furthermore, DDX11 role as a genome caretaker opens up the possibility to target it in personalised treatment of cancers, where synthetically lethal genome stability pathways are altered." (PMID 30469382, 2018). "Therefore, positive selection may drive the enhanced function of DDX11 by modifying the critical protein domains and increasing its expression, which could be hitchhiked by the highly proliferative cell cycles of cancer." (PMID 36474250, 2022). "This role of DDX11 in mitigating replication stress relies on its helicase activity and is especially relevant in replication stress conditions induced by DNA damaging drugs, correlating with the ability of cancer cells to tolerate the chemotherapy-induced DNA damage." (PMID 33879618, 2021). "However, if the DNA damage tolerance functions of DDX11 are relevant for tumorigenesis or cancer therapies remains currently unknown." (PMID 33879618, 2021). "However, the detailed mechanism through which DDX11 participates in the tumorigenesis and cancer progression remains largely unknown." (PMID 33614480, 2020). "Interestingly, among the top enriched terms that were associated with DNA damage response and cohesion related, supporting the hypothesis that DDX11 inhibition may be a good therapeutic target in cancer cells, many of which carry defects in DNA repair pathways." (PMID 38478595, 2024). "This is supported by the DDX11, DKC1, EXOSC5, NOP56, and other genes showing differences in the most cancer types." (PMID 36698399, 2022). "Patients who had DDX11-positive and TMEM38B-negative tumors had significantly higher chances of cancer-specific death (odds ratio [OR] 49.000; 95% confidence interval [CI] 3.765–637.794) and recurrence (OR 28.000, 95% CI 2.399–326.735)." (PMID 31963294, 2020). "We also analyzed the relationship between E2F1 and DDX11 expression in TCGA database and found that E2F1 expression was positively correlated with DDX11 expression in these cancers." (PMID 32332880, 2020). "For CSS, patients with cancer-specific death presented higher expression patterns of RGPD8, BAIAP2L1, and DDX11 and lower expression patterns of SLC16A9, FRAS1, AQP1, TMEM38B, and PRUNE2, in both the univariate and multivariate analyses." (PMID 31963294, 2020). "To explore the expression pattern of DDX11 in HCC, we first analyzed the DDX11 expression level both in mRNA levels based on TCGA (The Cancer Genome Atlas) datasets, and in protein levels based on Pan-cancer tissue microarray (TMA)." (PMID 32332880, 2020). "The synthetic lethal interaction between DDX11 and APC/C subunits could be exploited in novel therapeutic strategies for those cancers, where DDX11 expression is down-regulated." (PMID 30469382, 2018).
cancer (continued). "Notably, knockdown of DDX11 in several nonmalignant cell lines, namely in hTERT RPE-1 (retinal epithelial), MCF10A (breast), and BJ (fibroblasts), caused only minor effects and at higher drug concentrations than those affecting cancer cell lines." (PMID 33879618, 2021).
tumor (16 papers, 2016 to 2025). "We further prioritized 15 upregulated PSGs potentially implicated in tumor, among which, DDX11 has already been proposed to be a target for therapeutic interventions." (PMID 36474250, 2022). "Based on the similarity of VAFs one can speculate that the DDX11 variants were biallelic in the tumor clone." (PMID 31767937, 2019). "This study suggested the possible mechanisms linking VAT, DDX11, and tumor aggressiveness and provided support for future studies including in vitro experiments we are undergoing." (PMID 33823929, 2021). "DDX11 expression, which is involved in cell-cycle progression, is used to predict tumor aggressiveness in clinically localized T1-stage ccRCC." (PMID 33823929, 2021). "Our results showed that DDX11 expression and tumor size were significantly greater in patients with high Fuhrman grade (3 and 4), both in the univariate and multivariate analyses." (PMID 31963294, 2020). "Patients with high DDX11 expression were likely accompanied with shorter overall survival and experienced tumor relapse in shorter time." (PMID 33614480, 2020). "High DDX11 expression was positively correlated with large tumor size, tumor multiplicity, late tumor-node-metastasis (TNM) stage and poor prognosis." (PMID 32332880, 2020). "Since tumor hitchhiking of UC genes derived cell cycle-related uPSGs (including DDX11) may represent antagonistic pleiotropy, we wondered which normal biological processes recruit these cell cycle-related new genes under the force of positive selection." (PMID 36474250, 2022). "Notably, knockdown of DDX11 in PEO1 and Capan-1 sensitive (S) as well as resistant (R) clones rendered the BRCA2-mutated tumor cells sensitive to olaparib." (PMID 33879618, 2021). "In addition, immunohistochemistry studies carried out on tissue samples derived from an ADC patient cohort have revealed a positive correlation between DDX11 levels of expression and tumor size and stage." (PMID 33802088, 2021). "DDX11 is an important gene for predicting tumor aggressiveness based on the Fuhrman grade." (PMID 32392781, 2020). "Consistently, DDX11 is upregulated in tumour tissues of ADC." (PMID 31413739, 2019). "Furthermore, DDX11 expression was significantly positively related to tumour size and the TNM stage of the patients." (PMID 31413739, 2019). "Notably, genes, such as DDX11 (12p11.21), IGLV2-18 (22q11.22), OR8G5 (11q24.2), PARP4 (13q12.12), USP10 (16q24.1), and ZNF208 (19p12), exhibited multiple mutations and demonstrated tumor-driving effects." (PMID 39711964, 2024). "Thus, under the coordination of E2F, DDX11 interact with Timeless to support the tumor cell cycle." (PMID 36474250, 2022). "Some CSC marker genes showed extremely disparate expression levels between normal and tumor samples, such as PLCG2, DDX11, IER5L, LENG8, HAGHL and CPNE7." (PMID 37377935, 2023). "To further confirm the expression levels of DDX11 in HCC, we examined the DDX11 protein expression in 8 paired HCC and adjacent non-tumor specimens." (PMID 32332880, 2020). "Frozen tumor tissues and plasma were used to measure PBRM1, BAP1, SET domain-containing 2 (SETD2), KDM5C, FOXC2, CLIP4, AQP1, DDX11, BAIAP2L1, and TMEM38B mRNA levels, and correlation with the Fuhrman grade was investigated." (PMID 32392781, 2020). "Knockdown DDX11 inhibited HCC tumor growth, with significantly lower tumor weight and smaller tumor volume." (PMID 32332880, 2020). "Intriguingly, clinic pathological analysis indicated that high DDX11 expression was positively related to advanced TNM stage, poor histological differentiation, larger tumor size, and high vascular invasion potential." (PMID 32332880, 2020). "The determination of plasma SETD2 and DDX11 mRNA levels in the plasma can be used as a means of supplementing the low-grade accuracy of conventional RMB, by including ease, safety, and the ability to provide more information on the tumor." (PMID 32392781, 2020).
tumor (continued). "Functionally, DDX11 promoted cell proliferation by inducing the expression of EZH2, a famous oncogene, to subsequently inhibit the expression of p21, a well-known tumor suppressor." (PMID 33614480, 2020). "The results demonstrated that DDX11 mRNA was highly expressed in numerous tumour samples compared with its expression in non-tumour tissues." (PMID 31413739, 2019). "A prospective study examining frozen tissue qRT-PCR of AQP1, DDX11, BAIAP2L1, and six previously identified genes (PBRM1, BAP1, SETD2, KDM5C, FOXC2, and CLIP4) showed that expression of DDX11 was a significant factor for predicting tumor aggressiveness based on Fuhrman grade." (PMID 31963294, 2020).
infection (2 papers, 2018 to 2024). The state of being infected such as from the introduction of a foreign agent such as serum, vaccine, antigenic substance or organism. "In the present study, overexpression of DDX11 restricted SADS-CoV and VSV-GFP infection, whereas knockdown or knockout of DDX11 enhanced SADS-CoV and VSV-GFP replication." (PMID 39470258, 2024). "Because MAVS was localized in mitochondria and interacts with DDX11, we further isolated the mitochondrial fraction and observed increased localization of DDX11 to mitochondria in HEK293T cells after infection with SeV." (PMID 39470258, 2024). "This cell line (named HeLa 5–5) was established by infection with a pantropic retrovirus (pSuper-Retro-Puro) that expresses a shRNA targeting the DDX11 coding sequence." (PMID 30303954, 2018). "We next investigated whether aa 445–665 of DDX11 might regulate VSV-GFP infection and proliferation." (PMID 39470258, 2024). "Notably, knockout of DDX11 decreased the interaction among RIG-I and MAVS upon infection with SeV." (PMID 39470258, 2024).
DDX11 also shares sentences with these, for which no sentence is quoted: genetic disorder (6 papers); Roberts Syndrome (5); Cornelia de Lange syndrome (4); breast carcinoma (2); chronic atrial and intestinal dysrhythmia (2); adrenocortical carcinoma (1); Alpha-thalassemia (1); angiomyolipoma (1); Atelís Syndrome (1); CHOPS syndrome (1); colon cancer (1); colorectal cancer (1); esophageal cancer (1); Fanconi anemia complementation group J (1); gallbladder cancer (1); Hypercholesterolemia (1); idiopathic pulmonary fibrosis (1); Intellectual disability (1); melanoma in situ (1); nevus (1); Nijmegen breakage syndrome (1); oncocytoma (1); pancreatic adenocarcinoma (1); pancreatic cancer (1); rectum adenocarcinoma (1); systemic lupus erythematosus (1); trichothiodystrophy (1); uterine cancer (1).